MIR367 (microRNA 367)
Synonyms: hsa-mir-367; MIRN367
Gene: MicroRNA gene on chromosome 4 (112,647,874 to 112,647,941, reverse strand). Ensembl gene ENSG00000199169.
Gene Ontology:
Biological process: miRNA-mediated post-transcriptional gene silencing
Cellular component: RISC complex
Homologues: Orthologues: chimpanzee ptr-mir-367 (100% identical), rabbit MIR367 (99% identical), dog MIR367 (96% identical), macaque mml-mir-367 (96% identical), guinea pig MIR367 (74% identical), tropical clawed frog xtr-mir-367 (74% identical).
Diseases named in the same sentence as MIR367 in open-access papers:
MIR367 is named in the same sentence as 3 diseases in open-access papers, as found by Europe PMC text mining. Sharing a sentence is not in itself a finding about the gene and the disease. The quoted sentences say what the papers report.
colorectal cancer (1 paper, 2021). A primary or metastatic malignant neoplasm that affects the colon or rectum. "In turn, the CN regions contained three known microRNAs (MIR34A, MIR367 and MIR302A) that regulate the expression of genes involved in the pathogenesis of colorectal cancer." (PMID 34202891, 2021).
embryonal tumors (1 paper, 2021). "Interestingly, MIR367 was recently found to function as tumor promoting miRNA, since its inhibition attenuates tumor aggressiveness and proliferation in embryonal tumors." (PMID 34204289, 2021).
MIR367 also shares sentences with these, for which no sentence is quoted: tumor (1 paper).